MMP2 (matrix metallopeptidase 2)
Diseases named in the same sentence as MMP2 in open-access papers (continued):
Sharing a sentence is not in itself a finding about the gene and the disease.
Ewing sarcoma (4 papers, 2014 to 2019). A small round cell tumor that lacks morphologic, immunohistochemical, and electron microscopic evidence of neuroectodermal differentiation. "It is also well established that MMP2 and MMP9 are expressed in Ewing sarcoma and closely associated with Ewing sarcoma invasion and metastasis." (PMID 31370265, 2019). "However, all cell lines used in this study expressed both MMP2 and MMP14, suggesting that MMP14 influences Ewing sarcoma cell behavior." (PMID 31466240, 2019). "In order to determine whether ZA-induced inhibition of ES invasion was due to impaired MMP-2 and −9 activities, zymography assay was performed on culture supernatants of Ewing’s sarcoma cells treated or not with ZA." (PMID 24612486, 2014). "Also, the levels of expression of the well-known pro-angiogenic molecules (VEGF and b-FGF) and pro-invasive molecules (MMP-2 and MMP-9) were highly inhibited following combination of EWS shRNA plasmid transfection and TFL treatment in Ewing’s sarcoma xenografts." (PMID 27547487, 2014).
experimental autoimmune encephalomyelitis (4 papers, 2015 to 2022). An autoimmune demyelinating disease of the central nervous system that is produced experimentally in animals by the injection of homogenized brain or spinal cord in Freund's adjuvant. "Therefore, similarly to what was observed in experimental autoimmune encephalomyelitis, our data suggest that loss of MMP-2 activity in hepatic IRI exacerbated disease, in part, by augmenting MMP-9 secretion." (PMID 26355684, 2015). "An increase of MMP-9 expression in the absence of MMP-2 activity was previously observed in experimental autoimmune encephalomyelitis." (PMID 26355684, 2015).
Fibroadenoma (4 papers, 2017 to 2025). A benign tumor of the breast characterized by the presence of stromal and epithelial elements. "At 25 weeks, corresponding to fibroadenoma emergence, the Diet group showed increased expression of MMP2 (p = 0.036), THBS1 (p = 0.03), TWIST1 (p = 0.015), and PAI-1 (p < 0.001)." (PMID 40806434, 2025). "KRT5, TGF-β, PAI-1, HIF-1α, TIMP1, MMP2, TWIST1, VEGFα, and BRCA2 were all significantly upregulated in fibroadenomas." (PMID 40806434, 2025). "Few studies have evaluated the immunohistochemical expression of MMP-2 and MMP-9 in BC and fibroadenoma." (PMID 34445715, 2021). "Some authors have found significantly higher MMP-2 and MMP-9 protein expression in BC cells than in fibroadenoma." (PMID 34445715, 2021).
focal segmental glomerulosclerosis (4 papers, 2019 to 2022). A renal disorder characterized by sclerotic lesions in the glomeruli. "In fact, expression of MMP-2 and -9 was found to be altered in focal segmental glomerulosclerosis, membranous nephropathy, and vasculitis." (PMID 33573220, 2021). "Typical patterns of MMP-2 and MMP-9 are differentially expressed in patients with focal segmental glomerulosclerosis, minimal change disease, membranous nephropathy, and ANCA-associated vasculitis." (PMID 31963569, 2020). "Furthermore, it has been reported that MMP2 and MMP9 are differentially expressed in patients with minimal change disease, focal segmental glomerulosclerosis and membranous nephropathy." (PMID 35045102, 2022).
follicular thyroid cancer (4 papers, 2017 to 2020). "One interesting application of using PA exogenous contrast agents is detecting the PA signals of matrix metalloproteinase-2 (MMP-2) in follicular thyroid cancer." (PMID 31948442, 2020). "We have recently shown that calpains are of importance in the S1P-evoked secretion of MMP2/9 in follicular thyroid cancer ML-1 cells." (PMID 29734379, 2018). "The situation is quite similar to what we previously saw in follicular thyroid cancer ML-1 cells, where knock-down of MMP2 and -9 only partially inhibited the invasion in response to S1P." (PMID 29734379, 2018). "Interestingly, S1P promotes migration and invasion in human follicular thyroid cancer ML-1 cells and increases the secretion and activity of MMP2 and MMP9 through S1P1,3." (PMID 29734379, 2018). "In addition, S1P also decreased the expression, secretion and activity of MMP2 at 6 h and 8 h in thyroid follicular cancer FTC-133 cells." (PMID 29734379, 2018). "For example, a photoacoustic probe activated by MMP-2 and MMP-9 demonstrated sensing of MMP-2/-9 activity in a follicular thyroid carcinoma model." (PMID 28197395, 2017). "The production of MMPs has been monitored preclinically, with a probe cleaved by MMP-2 and MMP-9 giving an increase in PAI signal upon cleavage in preclinical models of follicular thyroid carcinoma, which express high levels of MMP-2, MMP-7 and MMP-9 compared to benign thyroid adenomas." (PMID 31337635, 2019).
gastritis (4 papers, 2008 to 2023). Inflammation of the stomach. "One study in adults with H. pylori-associated gastritis showed upregulated MMP-2, -9, and TIMP-2 on the surface of infiltrative mucosal lymphocytes." (PMID 37958643, 2023). "As a result, macrophage-related inflammatory mediators, including IL-1β, VEGF, IL-6, and MMP-2, all known to be engaged in either H. pylori-associated gastritis or carcinogenesis, were significantly increased in Group II." (PMID 26317548, 2015). "MMP2 levels were increased in the presence of HP infection and contributed to tissue damage in HP-associated gastritis." (PMID 18253117, 2008). "Higher MMP2 expression may lead to increased severity of chronic atrophic gastritis and subsequently less acid reflux and decreased EA risk." (PMID 18253117, 2008). "Our study also assessed mRNA for MMPs and TIMPs and the results revealed a higher expression of mRNA for MMP-9 along with a low expression of mRNA for MMP-2 in the gastric mucosa of children with H. pylori-related gastritis." (PMID 37958643, 2023). "Our data confirm that the main immune cellular source of MMP-2 in the peripheral blood of H. pylori-infected children with gastritis were lymphocytes and neutrophils, which demonstrated increased MMP-2 intracellular expression." (PMID 37958643, 2023). "It has been shown that MMP-2, -7 and -9, as well as MT1-MMP and TIMP-2 and -4, were upregulated in gastric mucosa biopsies from individuals with H. pylori–associated gastritis." (PMID 35163805, 2022). "Furthermore, adults with H. pylori-associated gastritis had increased levels of MMP-9 and decreased levels of MMP-2 and TIMP-1 in serum in comparison to healthy volunteers." (PMID 37958643, 2023). "Our first observation was that children with H. pylori-related gastritis showed increased levels of plasma MMP-2 and TIMP-2 in comparison to uninfected children with gastritis." (PMID 37958643, 2023). "In contrary to studies among children, adults with H. pylori–related gastritis have shown increased levels of MMP-8 and -9, an unchanged level of MMP-7, and decreased levels of MMP-2 and TIMP-1." (PMID 37958643, 2023). "In adults with H. pylori–related gastritis, increased levels of MMP-8 and -9, an unchanged level of MMP-7 and decreased levels of MMP-2 and TIMP-1 in comparison to healthy volunteers were detected in serum by using ELISA." (PMID 35163805, 2022).
HCMV infection (4 papers, 2010 to 2020). "Cytomegalovirus infection also inhibited migration of EVTs and resulted in a significant reduction in MMP-2 and MMP-9 expression compared with uninfected EVTs." (PMID 33374185, 2020). "After 48 h, it is observed that villus HCMV infection condition and the c-erbB-2, MMP-2 and MMP-9's expression levels in villus and characteristics of space distribution change." (PMID 21392403, 2011). "To determine whether reduction of MMP-2 production could inhibit TGF-β1 activation, we next transfected a GFP-expressing shRNA construct against MMP-2 mRNA into HK-2 cells prior to HCMV infection and raTGF-β1 stimulation." (PMID 21079788, 2010). "Since pro-MMP-2 is known to undergo activation in complex with other MMPs on the cell surface, we next performed immunoprecipitation experiments using lysates of HK-2 cells with or without HCMV infection and/or raTGF-β1 stimulation." (PMID 21079788, 2010).
Incisional hernia (4 papers, 2006 to 2021). An abdominal hernia that occurs at a site of weakness in the abdominal wall resulting from an incompletely-healed surgical wound. "In control, fibroblasts mesh incubation did not significantly affect MMP-2 expression, whereas polypropylene mesh contact of fibroblasts from patients with recurrent incisional hernias led to a major decrease of MMP-2 activity and of mRNA expression." (PMID 22481991, 2009). "There appears to be significant overexpression of MMP-2 in incisional hernia." (PMID 29950793, 2018). "Here, we found that incisional hernia fibroblasts exhibit a decreased MMP-2 gene expression." (PMID 17010202, 2006). "In primary fibroblast cultures obtained from skin scars of patients with and without recurrent incisional hernias, MMP-2 synthesis and gene expression were investigated." (PMID 22481991, 2009). "A former study of our group investigated the biomaterial induced MMP-2 mRNA expression in incisional hernia fibroblasts and detected no alterations of their MMP-2 synthesis compared to control fibroblasts." (PMID 17010202, 2006).
influenza (4 papers, 2008 to 2025). An acute viral infection of the respiratory tract, occurring in isolated cases, in epidemics, or in pandemics; it is caused by serologically different strains of viruses (influenzaviruses) designated A, B, and C, has a 3-day incubation period, and usually lasts for 3 to 10 days. "Zymography showed that smoke before influenza infection led to higher total activity of MMP-2, MMP-9 and caseinolytic proteases in BALF at d3." (PMID 18627612, 2008). "MMP-2 was slightly increased in smoke and influenza mice at d3." (PMID 18627612, 2008). "For both bioactive MMP-2 and MMP-9, we observed 1.9- and 1.3-fold increases early after infection (4 DPI), suggesting that both the placenta and the surrounding fetal membrane were subjected to enhanced MMP-mediated degradation as a result of influenza infection." (PMID 32922392, 2020).
intracranial aneurysm (4 papers, 2013 to 2022). "It has been reported that secreted protein acidic and cysteine-rich (SPARC) is highly expressed in intracranial aneurysms and is associated with the expression of EMT-related molecules (namely MMP2 and MMP9)." (PMID 34997174, 2022). "The results indicate that SPARC is widely expressed in human intracranial aneurysms, and its expression correlates with MMP-2 and MMP-9 expression, age and risk factors but not with the Hunt-Hess grade." (PMID 23516489, 2013). "Recent studies have shown that NF-κB p65 can promote inflammatory changes and regulate MMPs (MMP-1, MMP-2, MMP-3, and MMP-9) transcription participating in the initiation and progression of AAA and intracranial aneurysm (IA)." (PMID 26918963, 2016). "We found that the expression levels of SPARC, MMP-2 and MMP-9 were significantly up-regulated in intracranial aneurysms relative to the levels in normal Circle of Willis arteries." (PMID 23516489, 2013). "The results showed that SPARC, MMP-2 and MMP-9 were strongly expressed in intracranial aneurysm tissues; however, these proteins were expressed minimally or not at all in normal Circle of Willis arteries." (PMID 23516489, 2013). "The western blot results showed that the expression levels of SPARC, MMP-2 and MMP-9 were significantly up-regulated in intracranial aneurysms relative to the expression levels in the normal Circle of Willis arteries." (PMID 23516489, 2013). "Thirty-one intracranial aneurysms were immunohistochemically stained for SPARC, MMP-2 and MMP-9." (PMID 23516489, 2013). "Combined with previous research, the present study shows that SPARC regulates MMP-2 and MMP-9 expression in human intracranial aneurysms; however, whether SPARC is an upstream or downstream regulatory factor remains to be determined." (PMID 23516489, 2013). "The study showed that SPARC is widely expressed in intracranial aneurysms, and the expression of SPARC is significantly correlated with the expression of MMP-2 and MMP-9, which are by far the proteases that are the most closely related to the pathogenesis of intracranial aneurysms." (PMID 23516489, 2013). "The results showed that normal Circle of Willis arteries exhibited either minimal or negative staining for SPARC, MMP-2 and MMP-9; however, human intracranial aneurysms stained extensively for both SPARC and MMP-2/-9." (PMID 23516489, 2013).
invasive carcinoma (4 papers, 2008 to 2024). A carcinoma that is not confined to the epithelium, and has spread to the surrounding stroma. "In particular, MMP9 and MMP2 are involved in the degradation of type 4 collagen, which comprises basement membranes, a process thought to be important in the development of invasive carcinoma and metastasis." (PMID 18954444, 2008). "In particular, MMP9 and MMP2 (also know as gelatinases) are involved in the degradation of type 4 collagen that comprises basement membranes, a process thought to be important in the development of invasive carcinoma and metastasis." (PMID 18954444, 2008). "Upregulation of MMP-2 and MMP-9 expression and activity are the most common extracellular matrix-related modifications in precursor cervical lesions and invasive carcinoma." (PMID 38612895, 2024).
laryngeal squamous cell carcinoma (4 papers, 2017 to 2024). A squamous cell carcinoma that arises from the larynx. "Curcumin also prevented VEGF and MMP-2 production in laryngeal squamous cell carcinoma cells by reducing JAK2 and STAT3 phosphorylation and inhibiting angiogenesis." (PMID 37463912, 2023). "Oxymatrine is also capable of up-regulating miR-29b and down-regulating matrix metalloproteinase-2 (MMP-2) in cervical and laryngeal squamous cell carcinoma." (PMID 28208712, 2017). "Moreover, MMP-2 is more correlated with lymph node metastasis than MMP-9 in laryngeal squamous cell carcinoma." (PMID 32961679, 2020).
leukoaraiosis (4 papers, 2009 to 2023). "A recent study that genotyped MMP-2-1306 T/C and MMP-9-1562 C/T in a relatively large cohort of CSVD patients and controls came to a similar conclusion that MMP-2-1306 T/C polymorphism was associated with moderate or severe leukoaraiosis." (PMID 31474817, 2019). "Another study concluded that MMP-2-1306 T/C polymorphism was associated with moderate or severe leukoaraiosis." (PMID 31474817, 2019). "One mechanism potentially linking MMP-2 with increased IS incidence is its association with leukoaraiosis." (PMID 27529234, 2016). "Region 5, which illustrates univariate associations between the SNPs and leukoaraiosis, shows that four SNPs have significant, replicated and cross-validated associations (F3_rs3917643, CAPN10_rs7571442, MMP2_rs9928731, KITLG_rs995029)." (PMID 19351393, 2009). "MMP‐2/9 is involved in BBB degradation and MMP‐2 is associated with leukoaraiosis." (PMID 37452512, 2023).
meningitis (4 papers, 2004 to 2026). A disorder characterized by acute inflammation of the meninges of the brain and/or spinal cord. "We found a 10,000-fold increase of MMP-2 in CSF from patients with encephalitis, meningitis, and Ramsay Hunt syndrome which supports a previous study of VZV patients with CNS vasculopathies that also showed high levels of MMP-2 in CSF." (PMID 30777092, 2019). "MMP-2-levels increased 10,000-fold in CSF from patients with encephalitis, meningitis, and Ramsay Hunt syndrome and was the only MMP to be increased in all disease entities and also in CSF from all 67 patients." (PMID 30777092, 2019). "Overall, the findings suggest that MI altered MMP-2/3/9 activity, H3K4me3, and the methylation of Reln, thereby affecting reelin, synaptic protein expression, and motor coordination in an experimental meningitis rat model." (PMID 42123345, 2026). "We demonstrate that CNS complications caused by VZV virus are associated with highly elevated CSF levels of the chemokines CCL19, CXCL8, CXCL9, CXCL10, and the matrix metalloproteinase MMP-2 in patients with different CNS manifestations such as encephalitis, meningitis, and Ramsay Hunt syndrome." (PMID 30777092, 2019). "It is also established that most of the resident cells in human brain have the capacity to produce MMP-2 and MMP-9 – enzymes that are known to participate in brain damage (e.g. in case of infectious meningitis)." (PMID 15535833, 2004). "Similarly in a rat meningitis model dexamethasone did not influence parenchymal MMP-2 expression suggesting the MMP-2 gene may not be steroid responsive in the CNS." (PMID 21569377, 2011).
migraine (4 papers, 2014 to 2025). "There are also clinical studies showing that acupuncture can significantly reduce matrix metalloproteinase-2 (MMP-2) in migraine patients." (PMID 37542321, 2023). "The outcomes included the number of migraine attacks per week, the average duration of attacks, pain intensity assessed with the VAS scale, matrix metalloproteinase‐2 (MMP‐2) activity in serum, and quality of life measured with the SF‐36 questionnaire." (PMID 40237227, 2025).
myeloid leukemia (4 papers, 2018 to 2023). A clonal proliferation of myeloid cells and their precursors in the bone marrow, peripheral blood, and spleen. "The purpose of this study was to investigate the possible modulatory effects of ATRA on MMP-2 expression and secretion in human myeloid leukemia THP-1 cells." (PMID 30225259, 2018). "In this study, we examined the possible modulatory effects of ATRA on MMP-2 expression and secretion in human myeloid leukemia cell line THP-1." (PMID 30225259, 2018). "Taken together, our results suggest that ATRA induces calcium influx, which may be due to enhanced calcium-channel expression, and is involved in the induction of MMP-2 secretion in human myeloid leukemia THP-1 cells." (PMID 30225259, 2018). "In summary, our results show, for the first time, that ATRA enhances MMP-2 expression and secretion in human myeloid leukemia THP-1 cells in a calcium ion dependent manner through RAR-dependent and independent signaling pathways, and this enhanced secretion was reversed by dexamethasone treatment." (PMID 30225259, 2018). "However, our results revealed that ATRA enhances both MMP-2 expression and secretion in human myeloid leukemia THP-1 cells." (PMID 30225259, 2018). "Our results suggest that ATRA enhances MMP-2 expression and secretion in human myeloid leukemia THP-1 cells in a calcium ion dependent manner through RAR/RXR signaling pathways, and this enhanced expression and secretion may be associated with the possible mechanisms of RAS." (PMID 30225259, 2018).
ocular hypertension (4 papers, 2020 to 2025). Abnormally high intraocular pressure. "The present study also showed an increased level of MMP2 in the early stage of ocular hypertension, which may be triggered by ocular hypertension." (PMID 32719611, 2020).